FHIP2A (FHF complex subunit HOOK interacting protein 2A)
Description:
Required for proper functioning of the nervous system.
Synonyms: FAM160B1; KIAA1600; bA106M7.3
Tractability: PROTAC: ubiquitination databases record sites on it.
Gene: Protein-coding gene on chromosome 10 (114,821,744 to 114,899,832, forward strand). Ensembl gene ENSG00000151553.
Subcellular location (Human Protein Atlas): Nuclear speckles; Cytosol
Gene Ontology:
Molecular function: protein binding
Biological process: protein transport along microtubule
Cellular component: FHF complex
Genetic constraint (gnomAD): Loss-of-function variants: 31 observed, 62.65 expected, observed/expected ratio (o/e) 0.49, 90% interval 0.37 to 0.67. The upper end of that interval is the gene's LOEUF score, 0.67, which puts it in group 2 of 6, group 1 being the genes least tolerant of losing a copy. Missense variants: 587 observed, 722.31 expected, observed/expected ratio (o/e) 0.81, 90% interval 0.76 to 0.87. Synonymous variants: 250 observed, 258.78 expected, observed/expected ratio (o/e) 0.97, 90% interval 0.87 to 1.07.
Homologues: Orthologues: chimpanzee FHIP2A (99% identical), macaque FHIP2A (99% identical), dog FHIP2A (95% identical), pig FHIP2A (94% identical), mouse Fhip2a (93% identical), rat Fhip2a (93% identical), guinea pig FHIP2A (92% identical), rabbit FHIP2A (91% identical), tropical clawed frog fhip2a (81% identical), zebrafish fhip2a (75% identical), Drosophila melanogaster CG3558 (19% identical), Caenorhabditis elegans C05D11.8 (14% identical). Paralogues in human: FHIP2B (50% identical), FHIP1B (22% identical), FHIP1A (21% identical).
Diseases named in the same sentence as FHIP2A in open-access papers:
FHIP2A is named in the same sentence as 2 diseases in open-access papers, as found by Europe PMC text mining. Sharing a sentence is not in itself a finding about the gene and the disease.
FHIP2A shares sentences with these, for which no sentence is quoted: asthma (1 paper); leukemia (1).